NSD2 (nuclear receptor binding SET domain protein 2)
Diseases named in the same sentence as NSD2 in open-access papers (continued):
Sharing a sentence is not in itself a finding about the gene and the disease.
tumor (continued). "NSD2-dependent AR sites distinctively harbor the chimeric FOXA1:AR half-motif, which exclusively comprise tumor-specific AR enhancer circuitries defined from patient specimens." (PMID 39251788, 2024). "Among 31 single HMTs with expression in all samples, 19 showed a marked up-regulation in RB1-mutant tumours, with particularly notable up-regulation of EZH2, DOT1L, and NSD2, while only 5 displayed a clear down-regulation." (PMID 37883365, 2023). "Preclinical studies have identified both oncogenic and tumor-suppressing properties across NSD1, NSD2, and NSD3 within the context of HNSCC." (PMID 36360250, 2022). "Histone lysine methyltransferases, such as the H3K36 methyltransferase Whsc1/Nsd2 and the H3K9 methyltransferase G9a/Ehmt2, have been shown to play critical roles in tumor invasion and metastasis formation." (PMID 23520493, 2013). "For example, NSD2 enhances NFkB signaling by directly interacting with activated NFkB to promote transcription of downstream pro-survival genes such as IL6, CCND1, and BCL2, thereby promoting tumor growth." (PMID 41601922, 2026). "Furthermore, using CRC patient samples this study validated their findings and showed that NSD2 expression positively correlated with higher MHC-I expression, tumor-infiltrating T cells, and favorable prognosis." (PMID 40586874, 2025). "Conversely, NSD2 suppresses KRAS-driven pancreatic tumorigenesis by inducing the H3K36me2-dependent expression of IκBα, an inhibitor of NF-κB signaling, suggesting a putative tumor suppressive role." (PMID 41301842, 2025). "NSD2 overexpression also increased the expression of cyclin D, BCL2, and survivin via the positive feedback loop between NSD2 and NF-kB signaling, and promoted tumor growth and survival in castration-resistant prostate cancer." (PMID 41301842, 2025). "Multiplex immunofluorescence in additional prostatectomy and patient tumor specimens further confirmed the KRT8+/AR+ normal epithelial cells to have no detectable expression of NSD2, which was robustly expressed in the transformed epithelial cells." (PMID 39251788, 2024). "Consistently, combined NSD1 and NSD2 inhibition resulted in significant cytotoxicity in AR-positive PCa cells, whereas inactivation of either genes alone had little to no tumor-killing effect in prostatic cell lines." (PMID 39251788, 2024). "As shown, the mRNA expression levels for NSD2 and NSD3 are significantly elevated in tumor samples compared to normal samples, while quantification of protein levels reveal that NSD3 is upregulated in tumor samples." (PMID 37062069, 2023). "We also investigated the relationship between the levels of expression of NSD1, NSD2, or NSD3 with tumor-infiltrating lymphocytes (TILs) in either the HPV+ or HPV- HNSCC samples and whether expression of NSD1, NSD2, or NSD3 correlated with overall survival." (PMID 33588906, 2021). "Another interesting aspect that emerged from this study was the ability of NSD proteins, such as NSD2, to methylate non-histone substrates, in this case CD147, which can in a histone-modification-independent manner play a decisive role in controlling anti-tumor immunity." (PMID 40586874, 2025).
neurodevelopmental disorder (4 papers, 2020 to 2023). A behavioral and cognitive disorder with onset during the developmental period that involves impaired or aberrant development of intellectual, motor, or social functions. "Our report provides evidence to the role DNA methylation in the molecular etiology of NSD2 related neurodevelopmental disorders." (PMID 36589751, 2022).
hematological malignancies (3 papers, 2019 to 2025). "Consequently, NSD2 is frequently altered in several types of tumors—especially in hematological malignancies." (PMID 36232375, 2022). "Noteworthy, for some of these epigenetic effectors, such as NSD2 and PRMT5, there are small molecule inhibitors currently being tested in clinical trials for solid and hematological malignancies." (PMID 40504449, 2025).
heart diseases (2 papers, 2017 to 2019). "It will be important to identify these genes regulated by NSD2 which may provide new targets for the diagnosis and therapy of heart diseases." (PMID 30334333, 2019).
hematologic cancers (2 papers, 2022 to 2024). "As expected, hematologic cancers harboring activating NSD2 mutations emerged as the most sensitive to treatment with LLC0150 (IC50 ranging from 0.274 - 69.68 nM), which was immediately followed by AR-positive PCa cell lines (shown in red)." (PMID 39251788, 2024). "NSD2 is a bona fide oncogene in hematologic cancers and harbors recurrent activating alterations in over 15–20% of multiple myeloma and 10% of childhood acute lymphoblastic leukemia." (PMID 39251788, 2024).
psychiatric diseases (2 papers, 2020 to 2021). "Indeed, the isoform PPIs of the NSD2 indicate a potential distinguishing underlying mechanism, particularly for these exon-specific matched DNVs from patients with different psychiatric disorders." (PMID 33718354, 2021).
adenocarcinoma (1 paper, 2018). A common cancer characterized by the presence of malignant glandular cells. "While NSD2 was either not expressed or expressed at low levels in the non-lethal tumors, its expression increased dramatically in advanced disease stages and was particularly robust in the most aggressive phenotypes, namely CRPC adenocarcinomas and NEPC (p < 0.01, two-tailed Fisher's exact test)." (PMID 30518758, 2018).
blood tumors (1 paper, 2016). "The importance of NSD2 translocations in blood tumors has been previously demonstrated." (PMID 27604143, 2016).
CNS tumors (1 paper, 2022). "However, as NSD2 rarely been reported in CNS tumors, its significance in the occurrence and progression of MGNT is unclear." (PMID 35699689, 2022).
infection (1 paper, 2021). The state of being infected such as from the introduction of a foreign agent such as serum, vaccine, antigenic substance or organism. "After virus inoculation, the transgenic silkworm showed a remarkable susceptibility phenotype, suggesting that the candidate gene is nsd-2 itself, the virus resistance gene, and the complete membrane protein expressed by the allele, +nsd-2, is required for infection by BmBDV." (PMID 33801623, 2021).
neurological disorders (1 paper, 2017). "Although the downstream effectors of NSD2, such as RUNX2 and p300, which are known to play a role in bone development, have been identified, the mechanism by which NSD2 deficiency causes neurological disorders in patients with WHS is still unknown." (PMID 28665350, 2017).
NSD2 also shares sentences with these, for which no sentence is quoted: acute myeloid leukemia (3 papers); gastric cancer (3); autism (2); chronic lymphocytic leukemia (2); diffuse large B-cell lymphoma (2); glioblastoma (2); Hodgkins lymphoma (2); ovarian carcinoma (2); prostate (2); prostate adenocarcinoma (2); squamous cell carcinoma (2); -dependent (1); atherosclerosis (1); benign tumors (1); bladder cancers (1); bone marrow cancer (1); cancers of the brain (1); carcinoid (1); CHARGE syndrome (1); congenital heart malformation (1); convulsion (1); deafness (1); diffuse astrocytoma (1); endometrial tumors (1); Ewing sarcoma (1); Failure to thrive (1); genetic disorders (1); Glucose intolerance (1); growth deficiency (1); gynecological cancers (1).
A further 34 diseases each share a sentence with NSD2 in 1 paper.